PTPRZ1 (protein tyrosine phosphatase receptor type Z1)
Diseases named in the same sentence as PTPRZ1 in open-access papers (continued):
Sharing a sentence is not in itself a finding about the gene and the disease.
glioblastoma (continued). "Collectively, we found that PTPRZ1 expression positively correlates with AC-like and OPC-like glioblastoma states and glioblastoma stemness, and that its robust expression results in a high MHC ligand load in glioblastoma." (PMID 39893177, 2025). "The PTPRZ1-MET fusion has been identified in several types of cancer, mostly in glioblastoma and lung cancer." (PMID 39411129, 2024). "In the same line, PTPRZ1 is preferentially expressed in glioblastoma stem cells and seems to affect glioblastoma stem cell maintenance, while PTN binding to PTPRZ1 enhances the tumorigenic potential of these cells." (PMID 39409168, 2024). "The fourth largest subgroup, G6/Multi-RTK, was detailed by describing a novel gene fusion ST7–MET, rare PTPRZ1–MET, LMNA–NTRK1 and GOPC–ROS1 fusions and their overexpression mechanisms in glioblastoma." (PMID 38254850, 2024). "PTPRZ1-MET fusions have been found in brain tumors, such as low-grade gliomas, secondary glioblastomas arising in adults from the progression of lower-grade gliomas, and pediatric glioblastomas at a remarkably high frequency (~10%,)." (PMID 37760640, 2023). "Four of these seven cases relate to glioblastoma in which fusion pairs CAPZA2-MET and FIP1L1-PDGFRA, CAPZA2-MET and MET-MET, EGFR VIII and PTPRZ1-MET, PTPRZ1-MET and TBL1XR1-PIK3CA were identified." (PMID 35984852, 2022). "The PTPRZ1–MET fusion has been described in adult glioblastomas and entails the full length MET protein fused to the first exons of PTPRZ1 and probably uses its promoter to overexpress MET." (PMID 35169893, 2022). "Based on high-throughput sequencing, our team built the CGGA database and screened the PTPRZ1-MET fusion gene, which is expressed almost exclusively in secondary glioblastomas." (PMID 33329553, 2020). "We recapitulated distinct cellular states in a published glioblastoma dataset 41, and found PTPRZ1 expression to be enriched in astrocyte-like (AC-like) and oligodendrocyte-progenitor-like (OPC-like) glioblastoma cells and to positively correlate with their module scores." (PMID 39893177, 2025). "Similarly, in our own cohort, we found higher PTPRZ1 expression levels in AC-like and OPC-like glioblastoma cells." (PMID 39893177, 2025). "In addition to the robust in vivo efficacy of PTPRZ1-TCR-T, we found universal targeting of HLA-A*02+ primary glioblastoma cell lines and malignant cells in IPTOs with a preference for stem-like SCCs and AC-like tumor cells." (PMID 39893177, 2025). "To evaluate protein abundance, we analyzed n = 20 matched primary and recurrent glioblastoma samples and found patient-individual PTPRZ1 levels without temporal alterations between primary and recurrent tumors." (PMID 39893177, 2025). "Moreover, the fusion of the MET sequence at its 5′ end with PTPRZ1 gene exons creates the PTPRZ1-MET fusion, which has been reported in brain cancers, including secondary glioblastomas and low-grade gliomas." (PMID 39598385, 2024). "Although these fusions are rare in glioblastoma, the incidence in the Combined cohort being 0.5% for ST7–MET and LMNA–NTRK1, 1.1% for PTPRZ1–MET and GOPC–ROS1, and 1.6% for FGFR3 fusions, they appear to be targetable alterations that also occur in other solid cancers." (PMID 38254850, 2024). "In addition, our pipeline picked up several established fusions related to glioblastoma such as FGFR3-TACC3 and PTPRZ1-MET." (PMID 34745213, 2021). "PTPRZ1-MET and other MET fusions were also reported in pediatric glioblastoma." (PMID 31776899, 2020). "PTPRZ1 expression, notably of the receptor-type PTPRZ-B isoform, is up-regulated in gliomas and several studies have underscored that down-regulation of PTPRZ-B reduces glioblastoma growth in in vivo models." (PMID 29439552, 2018). "Notably, seven PTP genes (DUSP26, MTMR4, PTEN, PTPRM, PTPRN2, PTPRT and PTPRZ1) were differentially expressed between grade II-III gliomas and (grade IV) glioblastomas." (PMID 27586084, 2016).
glioblastoma (continued). "Interestingly, a broad range of actionable fusion genes were identified in this cohort of glioblastomas including EGFR-SEPT, EFGR intragenic recombination, FGFR3-TACC3, PTPRZ1-MET, CAPZA2-MET, METex14 skipping, AGK-BRAF, EGFR Viii, TBLXR1-PIK3CA and FIP1L1-PDGFRA." (PMID 35324914, 2022). "An additional receptor of IL-34, receptor-type protein-tyrosine phosphatase ζ (PTPRZ1, RPTP-ζ), was recently identified by Nandi and colleagues who showed signalling through PTPRZ1 by IL-34, but not CSF-1, in mouse brain and in the human glioblastoma cell line U251." (PMID 27898738, 2016). "In glioblastoma, exosomes derived from tumor cells harboring PTPRZ1-MET fusion conferred temozolomide resistance to recipient GBM cells, which was independent of O-6-methylguanine-DNA-methyltransferase levels." (PMID 31597943, 2019). "ICI non-responders were enriched in glioblastoma stem cells marked by SOX2 and PTPRZ1 and in cells marked by the IL-6 effector p-STAT3 in both pre- and post-ICI samples compared to ICI responders." (PMID 40161763, 2025). "Both PTPRZ1-positive and negative cells expressed canonical GSC markers in each of these populations, consistent with the earlier observation that different glioblastoma cell types express stemness markers." (PMID 34948008, 2021).
glioma (66 papers, 2005 to 2025). A benign or malignant brain and spinal cord tumor that arises from glial cells (astrocytes, oligodendrocytes, ependymal cells). "Another notable gene rearrangement is between MET and PTPRZ1, a gene encoding a tyrosine phosphatase, prevalent in certain brain tumors like low-grade gliomas and pediatric glioblastomas." (PMID 38675409, 2024). "PTPRZ1-MET fusion was reported to associate with glioma progression from low-grade to high-grade glioma, which was a target by a MET inhibitor vebreltinib." (PMID 37443050, 2023). "Interindividual levels of PTPRZ1 overexpression varied across patients but were found in all gliomas." (PMID 39893177, 2025). "More broadly, our findings underscore the therapeutic potential and relevance of ECM components such as GPC2, CSPG4, and PTPRZ1 as novel pan-glioma immunotherapy targets." (PMID 40517137, 2025). "When PTPRZ1 Glioma cells acted as receivers, the subclusters of astrocytoma showed a strong association with other cell types." (PMID 39403379, 2024). "Gliomasphere line specific (EGFR) and cell cycle markers (MKI67, TOP2A) dominated clustering and we noted enrichment of glioma stem cell (PTPRZ1, SOX2) and astrocytic markers (GFAP, S100B) in GS025." (PMID 38856710, 2024). "Yet, there is evidence suggesting that tumors harboring these gene fusions can be responsive to anti-MET monotherapy, as seen with PTPRZ1-MET in pediatric gliomas and KIF5B-MET in lung cancers." (PMID 38675409, 2024). "Ptprz1 has been primarily studied in tumors, particularly gliomas, where it inhibits tumor signaling pathways." (PMID 39635132, 2024). "Further analyzing TCGA PanCancer Atlas data, we confirmed that, in addition to breast cancer, PTPRZ1 is highly expressed in various cancer types, such as glioma, prostate, lung, esophageal, and select neuroendocrine tumors." (PMID 39518121, 2024). "In gliomas, PTPRZ1 expression is significantly upregulated and is being studied as a potential cancer driver and as a target for therapy." (PMID 37175798, 2023). "Experiments show that MET fusion proteins respond to anti-MET monotherapy: PTPRZ1-MET in a pediatric glioma and KIF5B-MET in lung cancers." (PMID 37760640, 2023). "During the last few years, there has been an increasing interest in the possible implication of PTPRZ1 in several malignancies, with most of the studies focusing on gliomas, in line with PTPRZ1 expression predominantly in the adult brain." (PMID 37175798, 2023). "An earlier study using mRNAs from 23 human glioma tissue samples showed that the transmembrane PTPRZ1 isoforms were expressed in all the lower-grade gliomas, but only in 45% of GBMs." (PMID 37175798, 2023). "More recently, HOXA5 has been shown to directly bind to the Ptprz1 promoter and upregulate its expression, resulting in increased glioma malignancy." (PMID 37175798, 2023). "GIMs can secret abundant pleiotrophin (PTN) to stimulate glioma stem cells (GSCs) through its receptor PTPRZ1 thus promoting GBM malignant growth through PTN-PTPRZ1 paracrine signaling." (PMID 36036011, 2022). "For example, PTPRZ1/PTN represents one of many spatially heterogeneous glioma:myeloid signaling nodes, and PTPRZ1/PTN signaling has been reported to promote glioma stem cell maintenance and glioma growth." (PMID 35140215, 2022). "In vitro work on PTPRZ-B knockdown cells showed that the N-terminal extracellular domain was sufficient to induce cellular migration (retained in the PTPRZ1-BRAF fusion) while the C-terminal is important for glioma proliferation in adults." (PMID 36503484, 2022). "In the pleiotrophin (PTN)‐PTPRZ1 paracrine signaling, which supports glioma progression, PTN released by TAMs binds to its receptor PTPRZ1 on GSCs, suggesting the significance of TAMs as important components of the CSC niche." (PMID 36226253, 2022). "One gene noteworthy is the PTPRZ1, which is a receptor tyrosine phosphatase recently found upregulated in a fusion transcript with the MET gene and associated to glioma progression." (PMID 29844869, 2018).
glioma (continued). "Here, the authors show that TAMs support glioma stem cell renewal via paracrine signalling to the pleiotrophin receptor PTPRZ1 and that blocking this axis results in increased survival of tumour-bearing animals." (PMID 28569747, 2017). "We recently examined the fusion landscape of WHO-grade II-IV glioma patients using RNA sequencing analysis, 214 fusion transcripts in 272 glioma patients were identified, and revealed a novel PTPRZ1-MET fusion transcript in secondary GBMs (sGBMs)." (PMID 29156757, 2017). "Consistently, in vivo limiting dilution assays showed that as low as 500 PTPRZ1+ glioma cells were sufficient to initiate the intracranial tumour growth, whereas a minimum of 5 × 103 PTPRZ1− glioma cells were required for tumour formation." (PMID 28569747, 2017). "Herein, we report that TAMs secrete abundant pleiotrophin (PTN) to stimulate glioma stem cells (GSCs) through its receptor PTPRZ1 thus promoting GBM malignant growth through PTN–PTPRZ1 paracrine signalling." (PMID 28569747, 2017). "PTPRZ1 is in fact overexpressed in both glioma subgroups as evident by the high RSEM RNA expression values." (PMID 27586084, 2016). "Many PTPRs play an important role as tumor suppressors, yet PTPRZ1 has a role in cell migration and tumor growth in vivo in glioma studies." (PMID 23170925, 2012). "Notably, depletion of PTPRZ1 results in significant impairment of glioma cell sphere formation in vitro and delays tumor growth in vivo, indicating a strong association of PTPRZ1 with glioma cell stemness." (PMID 39893177, 2025). "Additionally, Protein Tyrosine Phosphatase Receptor Type Z1 (PTPRZ1) emerged as a highly expressed ECM-associated target in pediatric HGG, which plays a key role in cell signaling, glioma progression, and immune modulation." (PMID 40517137, 2025). "In gliomas, PTPRZ1 takes part in cancer cell proliferation, migration, and invasiveness." (PMID 39893177, 2025). "Likewise, in human prostate cancer LNCaP and rat glioma C6 cells, the downregulation of the PTPRZ1 expression by siRNA resulted in a smaller increase in the cell migration induced by hypoxia or DMOG, respectively." (PMID 40361445, 2025). "Notably, integrin β4 expression exhibits significant positive correlation with PTPRZ1 expression in most of these cancer types with the exception of glioma, which uniformly displayed the highest level of PTPRZ1." (PMID 39518121, 2024). "Several signaling pathways such as the ß-catenin or the mTOR pathway have been shown to be among the downstream signaling pathways activated by PTPRZ1, and this activation occurs in glioma cells as well as in the stimulation of oligodendrocyte progenitor cell growth." (PMID 38275375, 2023). "This molecule inhibited rat C6 glioma cell proliferation and migration in vitro and inhibited tumor growth in vivo, favoring the notion that selective inhibition of PTPRZ1 may be a promising therapeutic approach in GBM." (PMID 37175798, 2023). "In a more recent study of the mRNA expression profiling of a series of clinical diffuse glioma samples of different grades, PTPRZ1 expression was found to be consistently upregulated in all glioma specimens, but it was significantly lower in GBM compared to lower-grade gliomas." (PMID 37175798, 2023). "Besides gliomas, PTPRZ1 is heterogeneously expressed in individual meningiomas and drives meningioma cell proliferation and tumorigenesis." (PMID 37175798, 2023). "Human gliomas are the most highly discussed tumors where PTPRZ1 is overexpressed and may regulate growth and invasion." (PMID 37175798, 2023). "This method could be used as the “gold standard” of ZM positive (ZM+) glioma diagnosis as the fusion point of PTPRZ1 and MET could be confirmed via Sanger sequencing included in this method." (PMID 33645009, 2021). "PTN and its target PTPRZ1 also may help promote stemness, signaling, and proliferation of neural progenitors and glioma tumor cells." (PMID 34101353, 2021).
glioma (continued). "PTPRZ1‐MET (ZM) is a critical genetic alteration driving the progression of lower‐grade glioma." (PMID 33645009, 2021). "Before we finally certified the glioma samples as ZM+, all the PCR product bands on agarose gel were purified and sequenced via Sanger sequencing followed by confirmation of the fusion point of PTPRZ1 and MET fragments." (PMID 33645009, 2021). "The receptors for EGF (EGFR) and PTN (PTPRZ1) have important roles in the genesis of gliomas." (PMID 33925547, 2021). "Consequently, the survival of mice co-implanted with PTPRZ1+ glioma cells and MLCs was shorter than that of the mice implanted with PTPRZ1+ glioma cells alone." (PMID 28569747, 2017). "We and others have shown that the encoded transmembrane PTP acts as an oncogene in gliomas and, interestingly, two HLA-presented peptides derived from PTPRZ1’s extracellular part are included in an experimental glioma vaccine that is currently explored in phase II clinical trials." (PMID 27586084, 2016). "Irrespective, PTPRZ1 expression is consistently up-regulated in all glioma specimens." (PMID 27586084, 2016). "We next investigated whether PTPRZ1 influence on cell migration is represented in our glioma models." (PMID 25238264, 2014). "The role of PTPRZ1 in glioma tumorigenesis has been extensively studied." (PMID 25360666, 2014). "Taken together, results demonstrate a dual oncogenic role for PTPRZ1 in glioma cells." (PMID 25238264, 2014). "If PTPRZ phosphatase activity would have been crucial for glioma cell proliferation, expression of an inactive ‘substrate protection’ mutant in PTPRZ1 knock-down cells might act dominant-negative and worsen the effect." (PMID 25238264, 2014). "PTPRZ1 is upregulated in gliomas, which likely contributes to enhanced tumor cell migration." (PMID 25238264, 2014). "The functions of Id4, OLIG1, and OLIG2 during normal development, and our data suggest that Id4 and potentially other proteins such as FABP7 and PTPRZ1 might account for the formation of distinct glioma subtypes during oncogenic progression." (PMID 16018821, 2005). "Based on the function of Id4, OLIG1, and OLIG2 during normal development, our data suggest that Id4 and potentially other genes such as Fabp7 and Ptprz1 might account for the formation of distinct glioma subtypes during oncogenic progression." (PMID 16018821, 2005). "Likewise, PTPRZ1 glioma cell/PTN myeloid cell interactions play a key role." (PMID 38712663, 2024). "Finally, in vivo studies showed that an anti-PTPRZ1 immunotoxin (7E4B11-SAP) could significantly delay human U87 glioma tumor growth in a mouse xenograft model." (PMID 25360666, 2014). "In contrast, key regulators of OPC specification and maintenance, including MYT1, OLIG2, PDGFRA, PTPRZ1, SMOC1, and SOX8 were hypomethylated in PM gliomas." (PMID 37055795, 2023). "GCL_TI specifically upregulates RG markers TNC, HOPX, PTPRZ1, and VIM, astrocyte markers CLU, LGALS1, as well as genes involved in migration and glioma network formation such as CD44, SPARC, and GAP43 (One peak)." (PMID 36823172, 2023). "To further illustrate the mechanism of MET hyperactivation in gliomas harboring ZM fusions, we analyzed the protein structure of the partner fragment of MET (the PTPRZ1 fragment) in PTPRZ1‐MET." (PMID 33645009, 2021). "In the PDGFRA#4 case, MET overexpression was most likely caused by the presence of a PTPRZ1-MET fusion, as PTPRZ1 is among the highest expressed genes in glioma, and the fusion places MET under the control of the PTPRZ1 promoter." (PMID 34572759, 2021). "MET alterations, including MET exon 14 skipping (METex14) and PTPRZ1-MET (ZM) fusion, in cell lines and xenografts demonstrated hyper-activation of the MET signaling pathway and acceleration of glioma proliferation." (PMID 32001707, 2020).